LGR5 (leucine rich repeat containing G protein-coupled receptor 5)
Diseases named in the same sentence as LGR5 in open-access papers (continued):
Sharing a sentence is not in itself a finding about the gene and the disease.
colon carcinoma (continued). "This is consistent with our previous report that DKK2 enhances Lgr5 expression in colon cancer." (PMID 38659853, 2024). "We hypothesized that one plausible mechanism for the inhibition of β-catenin signaling might be its interference with LGR5 expression, since LGR5 has been shown to be an essential part of a complex that potentiates β-catenin signaling in colon cancer cells." (PMID 37998393, 2023). "In this way, LIN28B promotes transformation and migration in colon cancer through LGR5, PROM1, and CDX2 mRNAs, promotes stemness and EMT in gastric cancer through NRP-1 mRNA, inhibits apoptosis in ovarian cancer through AKT2 mRNA, and promotes migration in neuroblastoma through MYCN-induced mRNAs." (PMID 37370851, 2023). "Likewise, we confirmed that patients with low LGR5 mRNA expression in their colon cancer tissues had a better five-year overall survival rate than patients with high LGR5 mRNA expression in their cancer tissues." (PMID 37998393, 2023). "MicroRNA (miR)-363 suppressed the translation of GATA binding protein 6 (GATA6), which functioned as a transcriptional factor to induce REG4 and leucine-rich repeat-containing G-protein coupled receptor 5 (Lgr5) expression essential for the growth of colon cancer cells under adherent conditions." (PMID 36172286, 2022). "Interestingly, specific repression of Furin in colon tumors induced by cancer cells with KRAS or BRAF mutation inhibited the expression of Nanog and LGR5 compared to wild-type KRAS and BRAF developed tumors." (PMID 35267511, 2022). "Furthermore, in normal colonic mucosa, GP strongly lowered CD133 with a modest effect on LGR5 (downregulation of CD133 and LGR5 is associated with growth inhibition of colon cancer cells)." (PMID 35956766, 2022). "Moreover, KINDLIN1 acts as an enhancer for the Leucine Rich Repeat Containing G Protein-Coupled Receptor 5 (LGR5) expression in colon cancer." (PMID 35096085, 2022). "Elimination of Lgr5 in colon cancer cells results to in reduced cell-cell adhesions." (PMID 36133922, 2022). "The search for activators of NF-κB signaling in the SI will thus continue in the future, but Tnfrsf19 is a potential candidate as it is expressed in SI crypts, is regulated by Wnt in Lgr5-positive CBCs and appears to modulate Wnt signaling in human colon carcinoma cell lines." (PMID 34751748, 2021). "In addition, CBX8 recruits KMT2B (lysine methyltransferases 2B) to the LGR5 promoter, which maintains H3K4me3 status to promote LGR5 expression, resulting in increased cancer stemness and decreased chemosensitivity in colon cancer." (PMID 34090418, 2021). "Besides Sox2 and ALDH, expression of several other surface proteins, such as CD44, CD133, Lgr5, CD24, EpCAM and ABCG2, has been associated with stemness features in the context of colon cancer." (PMID 32927726, 2020). "While Lgr5+ cells of normal crypts or colonic polyps which are non-precancerous lesions are located only at the bottom of the crypt, Lgr5+ cells of colon cancers and precancerous lesions like colonic adenomas are observed at all portions of glands in human cancer samples." (PMID 31947553, 2020). "In this study, we investigated the expression of putative cancer stem cell markers in pT4 colon cancer and revealed that patients with LGR5-negative tumours had a higher risk of post-operative peritoneal metastasis." (PMID 31000786, 2019). "Moreover, western blot and qRT-PCR results showed BCAR4high cells showed higher expression of NANOG, OCT4, SOX2, CD44, CD133 and Lgr5 which are important markers of CSC in colon cancer." (PMID 30962766, 2019). "Increasing evidence has demonstrated that Lgr5 marks a population of colon cancer CSCs." (PMID 31196164, 2019).
colon carcinoma (continued). "Expression of canonical Wnt target genes, such as the stemness marker Leucine-rich repeat-containing G-protein coupled receptor 5 (Lgr5) and osteopontin (Opn, Spp1) on mRNA level was significantly higher in SI and colon tumors in comparison to normal intestinal tissue." (PMID 31681563, 2019). "The colon stem cells, marked by the Wnt signaling enhancers Lgr5 and Ascl2, are usually confined at the base of the crypt in wild-type and miR-34a-/- mice but became enriched in C. rodentium-induced colon tumors in miR-34a-/- mice." (PMID 30543324, 2018). "Here, we determined whether leucine-rich repeat-containing G protein-coupled receptor 5 (LGR5), known as a stem cell marker for colon cancer and gastric cancer, can serve as a novel GSC marker involved in EMT and a therapeutic target in glioma." (PMID 30208924, 2018). "Importantly, spheroid cultures of these colon cancer stem cells contain an expression of other stem cell markers, such as LGR5, CD44, nuclear β-catenin and CD166." (PMID 29652830, 2018). "Thus, 4-Cl-HIPP can phenocopy CtBP2 knockout and inhibit the Wnt target and TIC marker LGR5, and also attenuate expression of the key oncogenic Wnt pathway target c-Myc in human colon cancer cells." (PMID 30197752, 2018). "Interestingly, epiregulin was expressed at the level of both LGR5+ and LGR5− colon cancer stem cells." (PMID 29652830, 2018). "(E) Western blot of Ascl2 and Lgr5 showing enriched colon stem cells in miR-34a-/- colon tumors." (PMID 30543324, 2018). "The relationship between Lgr5+ stem cells, shown in this study to be cells-of-origin for colon carcinoma and small intestine tumors, and Lgr5-expressing tumorigenic cells, which were observed to clonally expand, remains unclear." (PMID 28176811, 2017). "As for CD44, Lgr5 is a Wnt-regulated gene, a CSC marker required for the maintenance of CRC-derived liver metastasis and specifically associated to 5FU chemoresistance in colon cancer patients." (PMID 29354056, 2017). "Ablation of LGR5 in colon cancer cells and in intestinal crypt stem cells results in a disorganized cytoskeletal structure with loss of cortical F-actin, suggesting an intricate role for the receptor in cancer and for retaining stem cells within the intestinal stem cell niche." (PMID 28739799, 2017). "Intestinal stem cells and a subpopulation of colon cancer cells were shown to express Lgr5." (PMID 34221246, 2017). "This slow process may reflect the moderate malignant potential of LGR5+/KRASwt colon carcinomas, which are driven primarily by the intestinal SC program, and the longer period of time needed to acquire a more aggressive oncogene such as KRASmut." (PMID 26744320, 2016). "Lgr5 was identified as the putative marker of CSCs in colon cancers." (PMID 27557490, 2016). "Intriguingly, Kindlin-1 promoted the expression of LGR-5, a colon cancer stem cell marker." (PMID 27776350, 2016). "CD44 and Lgr5 has also been shown to be a marker of CSCs in colon cancer." (PMID 27894099, 2016). "These novel findings demonstrate that Lgr5+ stem cells are uniquely responsive to external dietary cues following the induction of DNA damage, providing a therapeutic strategy for eliminating damaged Lgr5+ stem cells to reduce colon cancer initiation." (PMID 27831561, 2016). "In addition, overexpression of Lgr5 in colon cancer and HEK293 cells decreases cell motility and stimulates cell-cell adhesion." (PMID 27187360, 2016). "Paradoxically, LGR5 ablation increased colon cancer cell invasiveness and xenograft tumorigenicity." (PMID 27314328, 2016). "Interestingly, a previous report suggests that in established human colon carcinomas, LGR5 expression remains basal and is exclusive from KRT20 expression." (PMID 25728748, 2015). "In addition, exogenous expression of LGR5 only partially rescues the tumorigenicity of colon cancer cells in which GATA6 was knocked down." (PMID 26387746, 2015).
colon carcinoma (continued). "LGR5 expression was found to be higher in colon cancer cell lines derived from metastatic tumors compared with those from primary tumors and correlated significantly with lymphatic invasion, vascular invasion, tumor invasion, lymph node metastasis and clinical stage." (PMID 25665511, 2015). "28, 29, 32, we found that REG4 and LGR5 expression was elevated in many colon tumors." (PMID 26387746, 2015). "The other hand, Lgr5 high expression was related to the poor prognosis in colon cancer." (PMID 26599100, 2015). "Analogous to and consistent with our current observations, LGR5 overexpression in colon cancer cell lines was shown to repress WNT pathway genes and to enhance expression of epithelial to mesenchymal transition genes, which together promote a stem-like phenotype." (PMID 24481423, 2014). "As enhanced invasive ability and chemotherapy resistance are critical features of CSCs, we examined whether LGR5 affected these features in colon cancer." (PMID 24789370, 2014). "Previous studies have shown that LGR5 was overexpressed in colon cancer tissue." (PMID 24789370, 2014). "Lgr5 has also been detected in tumor spheres derived from colon cancer." (PMID 23153436, 2012). "LgR5 has been demonstrated to be involved in the pathogenesis of different human cancer entities, including hepatocellular carcinoma, basal cell carcinoma, endometrial cancer, colon cancer and ovarian cancer." (PMID 21345220, 2011). "LGR5/GPR49 is overexpressed in tumors of the colon, ovary and liver and in basal cell carcinomas." (PMID 21978106, 2011). "Isolation of CSCs from colon carcinomas can be accomplished by selection of a subpopulation of tumor cells based on expression of one or multiple cell surface markers associated with cancer stemness, like CD133, CD44, CD24, CD29, CD166 and Lgr5." (PMID 21311095, 2010). "Furthermore, DPEP1 also could enhance the expression of colon cancer stem cell markers (LGR5, CD133, and CD44), which strengthened the tolerance of colon cancer cells to chemotherapy drugs." (PMID 35670012, 2023). "Notably, LGR5 functions as a tumor suppressor during colon cancer progression." (PMID 37686516, 2023). "Our data indicate that suppressing K-RasG13D mutation in colon cancer cells with a pre-clinical G12C inhibitor S7333 can reduce the cell proliferation but promote their stemness including spheroid formation, stem marker CD133, K-Ras, and stem gene Lgr5 expressions." (PMID 36386200, 2022). "Thus, targeted therapy for Lgr5+ cells in colon cancer might prevent the formation of colon adenoma or inhibit the progression of early-stage colon cancer." (PMID 31947553, 2020). "In a colon cancer model HMW-HA binding to TLR4 on cancer cells blocks TLR4 activation by LPS.This raises a question as to whether endogenous HA binding to TLR4 on the basolateral surface of LGR5+ crypt epithelial cells blocks TLR4 activation by LPS." (PMID 33552081, 2020). "LGR5 might be applicable as a clinical biomarker to identify patients who can benefit from aggressive management strategies against peritoneal recurrence of colon cancer." (PMID 31000786, 2019). "Notably, our analysis further revealed that the association between the LGR5 expression and the intestinal SC signature was observed only in the context of KRASwt but not KRASmut colon tumors." (PMID 26744320, 2016). "Thus, the miR-363-GATA6-REG4/LGR5 signaling cascade may serve as a new therapeutic target for patients with colon cancer." (PMID 26387746, 2015). "Silencing lgr5 expression could promote colon cancer cell apoptosis and reduced the metastasis." (PMID 26599100, 2015). "Targeting LGR5 may be an effective therapeutic strategy for eliminating colon cancer." (PMID 24789370, 2014). "Therefore, it is suggested that the increased expression of Lgr5 may be a positive marker of SP cells in the Colo205 colon cancer cell line." (PMID 23153436, 2012).
colon carcinoma (continued). "Oleic acid, linoleic acid and palmitic acid have been shown to modulate BMP-2, beta-catenin, LGR-5, Jagged 1, Ki-67 expression; affects Wnt, Notch and BMP signaling pathways in colon cancer." (PMID 41346617, 2025). "Strikingly, most of the Wnt genes upregulated by HMGA1 in our murine model are also upregulated in human colon cancer, including the WNT effectors, ASCL2, AXIN2, CTNNB1, MYC, EPHB2, CD44, and ETS2 and the WNT receptors, LGR5, LRP5, and LRP6." (PMID 39895630, 2025). "Correlations between levels of PRSS3 and PRSS22 mRNAs and CEA, CXCL16, CXCL17, GPR35 V2/3, LGR5, LGR6 and KLK6 mRNA levels in lymph nodes of colon cancer patients." (PMID 40909962, 2025). "CASC15 has been observed to regulate the expression of leucine-rich repeat-containing G-protein coupled receptor 5 (LGR5) by targeting miR-4310, thereby activating the Wnt/β-Catenin signaling pathway in colon cancer." (PMID 39519092, 2024). "Correlations between LGR6 mRNA expression levels and expression levels of LGR4, LGR5, CEA and CXCL16 mRNAs in lymph nodes of colon cancer patients." (PMID 38715790, 2024). "Lgr5, ALDH1, and EpCAM also play a crucial role in the maintenance of CSCs and are potential therapeutic targets for colon cancer." (PMID 37639070, 2023). "To confirm that LGR5 and DCLK1 are both colon cancer stem cell markers and are related to WNT5A signaling, we studied colony and spheroid formation of colon cancer cells, assays used to demonstrate the presence of cancer stem cells." (PMID 37998393, 2023). "To fully evaluate such a possible inconsistency between the cancer stem cell markers LGR5 and DCLK1, we also investigated the expression and prognostic value of DCLK1 in the two colon cancer cohorts and how it correlated with WNT5A expression." (PMID 37998393, 2023). "These reduced expression levels of LGR5 and RSPO3 occurred in parallel with reduced expression levels of unphosphorylated (active) β-catenin and its downstream target VEGFA in colon cancer cells." (PMID 37998393, 2023). "Based on the elevated levels of both LGR5 and RSPO3 in colon cancer tissues, we performed an analysis that revealed positive correlations between RSPO3 and LGR5 at both the protein and mRNA levels." (PMID 37998393, 2023). "In the GSE44076 colon cancer cohort (N = 198), we next investigated a possible correlation between WNT5A mRNA and LGR5 mRNA expression." (PMID 37998393, 2023). "LGR5 and CD44 are potential markers for isolating colon cancer stem cells (CSCs), which promote proliferation and tumor formation." (PMID 35269806, 2022). "Results of quantitative real-time polymerase chain reaction (qRT-PCR) showed that LGR5 and VSIG4 were differentially expressed between normal and colon cancer samples." (PMID 36186438, 2022). "To further explore if the increased stemness in colon cancer will relate to tumor recurrence and metastasis, we employed the public database to analyze the correlation between CD133 and Lgr5 and other relevant gene expressions." (PMID 36386200, 2022). "Expression levels of LGR5, VSIG4, GZMB, and ITLN1 were tested in colon cancer and adjacent normal tissues via qRT-PCR method." (PMID 36186438, 2022). "To explore the functional roles of LGR5 in HGSC, we screened 4 HGSC cell lines and found that LGR5 mRNA levels were extremely low in all of them compared to the colon cancer cell lines, LoVo and SW620." (PMID 35778589, 2022). "The mRNA expression of the CSC markers, LGR5 and NANOG, were significantly induced in the spheres of the colon cancer cell lines SW480, SW620, CT-26 and HT-29, compared to their parental cells." (PMID 35267511, 2022). "Through upregulating LGR5, METTL3 participated in regulating stemness and chemosensitivity of colon cancer." (PMID 34345203, 2021).
colon carcinoma (continued). "For instance, a high-fat diet drives LGR5 expression, ISC transformation, and tumorigenesis in mice colon cancer via an increase in vitamin A-bound serum retinol-binding protein 4-stimulated by retinoic acid 6 (RBP4-STRA6) signaling pathway." (PMID 33827616, 2021). "In particular, in colon cancer, CCSCs have been identified in established colon cancer cell lines or in primary tumors through their expression of CD133, CD44, CD166, Lgr5, EpCAM, ALDH1 and β-catenin alone or through combinations of these markers." (PMID 33819194, 2021). "Currently, colon cancer stem cell (CCSC) populations have been isolated and identified by several markers, such as CD133, CD44, CD166, Lgr5, EpCAM, ALDH1 and β-catenin." (PMID 33819194, 2021). "The mRNA expression levels of the colon cancer-specific stemness markers DCLK1, LGR5, and ALDH1A1 were elevated in HT-29 as well as in Caco-2 cell-derived colonospheres and were downregulated after LTC4 stimulation." (PMID 32814764, 2020). "Lgr5 has also shown to be directly involved in the activation of TGF-β signaling and suppression of colon cancer metastasis." (PMID 31901081, 2020). "Here, mRNA expressions were analyzed for TETs, LGR5 and BMI1 in CSCs isolated from human colon cancer samples." (PMID 31057717, 2019). "Consistently higher expression of CD133, SOX2, NANOG, OCT4, CD44 and Lgr5 in ALDH+ cells, which was the representative markers of CSC, validated the truth of stemness of ALDH+ colon cancer cells." (PMID 30962766, 2019). "Both intestinal and colonic tumors also stained positive for migrating cancer stem cell markers CD110 and CDCP1 and Lgr5, respectively." (PMID 31040926, 2019). "Here we have shown that γ-Mangostin decreases expression of both LGR5 and DCLK1 in colon cancer cells along with inhibition of colonosphere formation." (PMID 31608135, 2019). "Of these, we selected miR-142-3p from the 50 microRNAs, as this was the only microRNA that promoted the formation of colon cancer stem-like spheres and the expression of CD133 and Lgr5 by FCM." (PMID 30220706, 2018). "In fact, Zhou and coworkers showed that the maximum LGR5 expression was observed in stage I and II colon cancer and progressively decreased in stage III and IV colon cancers." (PMID 29652830, 2018). "They revealed that the cell populations characterized by distinct gene signatures, such as immature progenitor (LGR5+/ASCL2+) and goblet-like cell (MUC2+/TFF3high) signatures exist in both colon tumors and normal intestine." (PMID 29064439, 2017). "In colon cancer, tumors with constitutive LIN28B expression exhibit increased expression of colorectal stem cell markers, LGR5, KIT and PROM1 (CD133)." (PMID 29064439, 2017). "ABCB5, Lgr5, CD133, and CK20 gene expression in bone marrow collected from patients with colon cancer was further quantified and tested for their influence on overall survival in the patients." (PMID 34221246, 2017). "The AS of CALD1, COL6A3, FN1, MAST2, LGR5 and ITGB4 were previously validated in colon cancer using RT-PCR24, while CLSTN1, AUP1, CTNND1, CALD1 and COL6A3 were shown to exhibit tumour-specific splice variants in colon, bladder and prostate cancers." (PMID 28592875, 2017). "Next, the clonality of Lgr5+ or Bmi1+ cell-derived small intestine tumors was examined using the FAP model, which provided similar results as with colon tumors." (PMID 28176811, 2017). "The levels of expression of the bona fide colon cancer WNT-TCF activity biomarker AXIN2, as well as the WNT-regulated stem cell markers LGR5 and ASCL2, were determined by RT-qPCR in transduced cells in vitro and in subcutaneous xenografts." (PMID 26939070, 2016). "Whereas there were small context-dependent differences, the canonical and bona fide colon cancer WNT-TCF targets AXIN2 and LGR5 were generally repressed at 5μM CAP2 (batch 2)." (PMID 27973612, 2016).